MIR5193 (microRNA 5193)
Synonyms: hsa-mir-5193; mir-5193
Gene: MicroRNA gene on chromosome 3 (49,806,137 to 49,806,245, reverse strand). Ensembl gene ENSG00000283726.
Homologues: Orthologues: chimpanzee MIR5193 (100% identical).